GPC3 (glypican 3)
Diseases named in the same sentence as GPC3 in open-access papers (continued):
Sharing a sentence is not in itself a finding about the gene and the disease.
cancer (continued). "Here, a cancer-wide GPC expression study, using clinical cancer patient data in The Cancer Genome Atlas, reveals net upregulation of GPC1 and GPC2 in primary solid tumors, whereas GPC3, GPC5 and GPC6 display lowered expression pattern compared to normal tissues." (PMID 36944188, 2023). "The GPC3 vaccine was used in combination with CAR-T therapy, to significantly enhance the therapeutic effect against OC, suggesting that the GPC3 vaccine could be used in combination with several cancer treatments in the future." (PMID 36826026, 2023). "Whether or not FAT1 regulates GPC3 expression during human embryonic development and cancers is a question that remains to be explored." (PMID 33878524, 2021). "Interestingly, GPC3 can interact with Wnt molecules independent of HS chains and accelerate cancer cell division by activation of canonical Wnt signaling pathway." (PMID 33344222, 2020). "The findings to date indicate that these TCR-iPS-T cells derived from an HLA homozygous iPS cell stock showed both cancer antigen-specific cytotoxic effects caused by CAR and non-specific cytotoxicity due to stimulation of natural killer cell ligands against GPC3-positive cell lines." (PMID 31024850, 2019). "Further, EGb could decrease the levels of alpha-fetoprotein (AFP), glypican-3 (GPC-3) and carcinoembryonic antigen (CEA) in HCC rats, suggesting that the anti-cancer efficacy of EGb was induced through its anti-proliferative and apoptotic properties in the HCC animal model." (PMID 29344418, 2017). "Compared with GPC-1, GPC-2, GPC-3, and GPC-5, few studies have investigated the mechanism and prognostic significance of GPC-4 and GPC-6 expressions at the mRNA level in malignant tumors, and no related reports have been found in HCC." (PMID 33902495, 2021). "Notably, potent anti‐cancer cytotoxicity was confirmed against Hep3B cells which were GPC3‐positive, whereas minimal cytotoxicity was observed with PLC/PRF/5 cells which were detected as GPC3‐negative." (PMID 41267637, 2025). "However, both large and small carcinoma cells were totally c-Kit-negative, CD34-negative, αSMA-partially positive, PLAP-positive, SALL4-focally positive, AFP-negative, CD30-negative, glypican-3-slightly positive and Oct3/4-negative using immunohistochemical staining." (PMID 32990826, 2020).
infection (12 papers, 2012 to 2025). The state of being infected such as from the introduction of a foreign agent such as serum, vaccine, antigenic substance or organism. "Flow cytometry showed that after Ad-IL-12 or Ad-GPC3 infection, compared with the control cells, the expression level of IL-12 or GPC3 in 293 cells was significantly increased." (PMID 36139670, 2022). "TNF-α expression levels were high during the P.y-GPC3 infection on the 1st, 7th or 14th different days and were significantly different from those of uninfected mice (all P ≤ 0.01)." (PMID 28445973, 2017). "After 25 days of infection, the growth of the tumors was still clearly suppressed in the P.y-GPC3-infected mice compared to the P.y-WT (P < 0.05) and control mice (P < 0.001)." (PMID 28445973, 2017). "Infection with P.y-WT or P.y-GPC3 led to a decrease in percentage of splenic CD8α- CD11C+ DCs compared with uninfected mice (0.486% or 0.578%, vs 2.23%)." (PMID 28445973, 2017). "We performed one (MDA-MB231-GPC3×1) or two (MDA-MB231-GPC3×2) rounds of infection with lentivirus containing the GPC3 cDNA or with the empty vector (MDA-MB231-vector) as control." (PMID 27507057, 2016). "Interestingly, a previous study showed the GPC3 heparan sulfate proteoglycan was upregulated at the transcript level in HepG2-A16 cells upon infection with irradiated sporozoites." (PMID 30891005, 2019). "We followed a vaccination schedule for the mice to check whether infection with P.y-GPC3 induced a GPC3-specific CTL response." (PMID 28445973, 2017). "Additionally, genes related to cell adhesion such as ADGRF5, CAVIN2, FAT3, FILIP1, GSN, and TSPAN11 were downregulated in both the variants at 24hpi whereas CAV1, CAVIN1, GPC3, POSTN, SUSD2, and TSPAN7 were downregulated only after Delta variant infection at 24 hpi." (PMID 41200555, 2025). "Infection of LTEP-s and SK-MES-1 cells with lentivirus vector-GPC3 significantly increased GPC3 expression compared with cells treated with vector-NC." (PMID 31160489, 2019). "Three HLA-A2-restricted GPC3 antigenic peptides were synthesized, with GPC3522-530 FLAELAYDL and GPC3102-110 FLIIQNAAV antigenic peptide-modified DCs inducing CTL production, and exhibiting strong targeted killing ability in LUSC cells at 80 : 1 multiplicity of infection." (PMID 37965271, 2023). "Surprisingly, unlike its peak happened in the 7th day of P.y-WT infection, IFN-γ had a peak in the first day of P.y-GPC3 infection (both P ≤ 0.01)." (PMID 28445973, 2017).
adenocarcinoma (10 papers, 2013 to 2026). A common cancer characterized by the presence of malignant glandular cells. "The glandular component consisted of a well-to-moderately differentiated adenocarcinoma with clear-cell morphology and enteroblastic features, showing positivity for glypican-3 and SALL4 with focal alpha-fetoprotein expression." (PMID 41969299, 2026). "Archived formalin-fixed paraffin-embedded tissues from the surgical resections of all 72 adenocarcinomas and 20 NETs were tested with immunohistochemistry targeting GPC3 and CK19." (PMID 39598037, 2024). "In parallel, the immunohistochemical profile of these adenocarcinomas is characterized by the loss of INI-1 expression, positivity for CK7, CK20 (focal) and CDX2 (focal), as well as positivity for yolk sac markers like glypican-3, alpha fetoprotein and SALL4." (PMID 35326613, 2022). "In the case of RECK, CRISPLD2, HPGD, GATA3 and GPC3, the signal related to the expression of the protein was down regulated in more than 45% of adenocarcinomas compared to surrounding healthy pneumocytes." (PMID 24265725, 2013). "The immunohistochemical profile of these adenocarcinomas is more complex, and, besides the loss of INI-1 expression, includes positivity for CK7, CK20 (focal) and CDX2 (focal), as well as for yolk sac markers including glypican-3, alpha fetoprotein and SALL4." (PMID 35326613, 2022). "The progressive accumulation of Glypican-3 in the adenocarcinoma extracellular environment may be explained by the release of Glypican-3 from the cell membrane." (PMID 26517809, 2015). "Since almost no tumors expressed GPC3, and all adenocarcinomas expressed CK19, we did not carry out clinical follow-up or a statistical analysis to correlate the expression of these markers with stage, grade, or overall survival." (PMID 39598037, 2024). "GPC3 protein and mRNA expression were positive in 55% of squamous cell carcinoma versus 8% of adenocarcinoma, but negative in normal lung tissues." (PMID 28510121, 2017).
benign tumors (3 papers, 2017 to 2024). "Our observation that GPC3-positive HCCs were softer than GPC3-negative HCCs seems counterintuitive at first glance, considering that malignant liver lesions usually have higher stiffness than benign tumors." (PMID 36518314, 2022).
metabolic disorders (2 papers, 2023 to 2026). "GPC3, which was one of the best candidates for PC in our study, has been previously associated to longevity and metabolic disorders in Holstein cows; both traits could be related to milk composition." (PMID 37337145, 2023).
genetic disease (1 paper, 2021). "Moreover, in Simpson–Golabi–Behmel syndrome, a human genetic disease characterized by overgrowth, where aberrant function of GPC3 affects Hh signaling, none of the other glypican family members can substitute for GPC3." (PMID 33742285, 2021).
immune disease (1 paper, 2010). "The discovery of GPC-3 protein in non-malignant adult tissue, whether inflamed liver or mature DC, challenges the hypothesis that GPC-3 is a potential target TAA for HCC immunotherapy because of the spectre that the generation of GPC-3-reactive T cells would induce auto-immune disease." (PMID 20465843, 2010).
GPC3 also shares sentences with these, for which no sentence is quoted: prostate carcinoma (9 papers); Merkel cell carcinoma (3); multiple myeloma (3); synovial sarcoma (3); Autoimmunity (2); brain cancer (2); chromophobe carcinoma (2); craniosynostosis (2); digestive system tumors (2); esophageal (2); fibrosis (2); hepatitis C (2); leukaemia (2); neuroendocrine carcinoma (2); neuroendocrine tumor (2); ovarian serous adenocarcinoma (2); pediatric tumors (2); Sepsis (2); triple-negative breast carcinoma (2); /malformation syndrome (1); acinar cell carcinoma (1); acromegaly (1); acute lymphocytic leukemia (1); Axenfeld-Rieger syndrome type 3 (1); B-cell lymphoma (1); Beckwith-Wiedemann syndrome (1); benign salivary gland tumors (1); biliary atresia (1); bladder cancer (1); Bosch-Boonstra-Schaaf optic atrophy syndrome (1).
A further 68 diseases each share a sentence with GPC3 in 1 paper.